IL1B (interleukin 1 beta)
Description:
Potent pro-inflammatory cytokine. Initially discovered as the major endogenous pyrogen, induces prostaglandin synthesis, neutrophil influx and activation, T-cell activation and cytokine production, B-cell activation and antibody production, and fibroblast proliferation and collagen production. Promotes Th17 differentiation of T-cells. Synergizes with IL12/interleukin-12 to induce IFNG synthesis from T-helper 1 (Th1) cells. Plays a role in angiogenesis by inducing VEGF production synergistically with TNF and IL6. Involved in transduction of inflammation downstream of pyroptosis: its mature form is specifically released in the extracellular milieu by passing through the gasdermin-D (GSDMD) pore. Acts as a sensor of S.pyogenes infection in skin: cleaved and activated by pyogenes SpeB protease, leading to an inflammatory response that prevents bacterial growth during invasive skin infection.
Synonyms: IL1F2; IL-1B; IL1-BETA; IL-1; IL1beta
Tractability: Small molecule: a structure with a bound ligand is known; a high-quality ligand is known. Antibody: an approved drug acts on it; UniProt places it where antibodies can reach, with high confidence; its Gene Ontology location is reachable by antibodies, with high confidence. PROTAC: a small molecule that binds it is known. Other modalities: an approved drug acts on it.
Target class: Secreted protein
Safety:
Unwanted effects reported when the protein is acted on. In parentheses: how it was acted on, where the effect was seen, and who reports it.
drug toxicities (source: ClinPGx)
peptic ulcer (source: ClinPGx)
weight gain (source: ClinPGx)
Gene: Protein-coding gene on chromosome 2 (112,829,751 to 112,836,816, reverse strand). Ensembl gene ENSG00000125538.
Subcellular location: Cytoplasm, cytosol; Secreted; Lysosome; Secreted, extracellular exosome
Pathways (Reactome):
Immune System: CASP4-mediated substrate cleavage; CASP5-mediated substrate cleavage; CLEC7A/inflammasome pathway; Interleukin-1 processing; Interleukin-1 signaling; Interleukin-10 signaling; Interleukin-4 and Interleukin-13 signaling
Disease: Purinergic signaling in leishmaniasis infection
Programmed Cell Death: Pyroptosis
Gene Ontology:
Molecular function: cytokine activity; integrin binding; protein binding; protein domain specific binding; interleukin-1 receptor binding; receptor ligand activity
Biological process: cellular response to mechanical stimulus; cellular response to xenobiotic stimulus; cytokine-mediated signaling pathway; defense response to Gram-positive bacterium; hyaluronan biosynthetic process; inflammatory response; interleukin-1-mediated signaling pathway; monocyte aggregation; negative regulation of cell population proliferation; negative regulation of extrinsic apoptotic signaling pathway in absence of ligand; negative regulation of gap junction assembly; negative regulation of lipid catabolic process; positive regulation of angiogenesis; positive regulation of canonical NF-kappaB signal transduction; positive regulation of cell migration; positive regulation of cell population proliferation; positive regulation of complement activation; positive regulation of DNA-templated transcription; positive regulation of epithelial to mesenchymal transition; positive regulation of ERK1 and ERK2 cascade; positive regulation of gene expression; positive regulation of glial cell proliferation; positive regulation of granulocyte macrophage colony-stimulating factor production; positive regulation of heterotypic cell-cell adhesion; positive regulation of inflammatory response; and 57 more
Cellular component: extracellular region; lysosome; cytosol; secretory granule; vesicle
Genetic constraint (gnomAD): Loss-of-function variants: 11 observed, 28.35 expected, observed/expected ratio (o/e) 0.39, 90% interval 0.24 to 0.64. The upper end of that interval is the gene's LOEUF score, 0.64, which puts it in group 2 of 6, group 1 being the genes least tolerant of losing a copy. Missense variants: 235 observed, 320.88 expected, observed/expected ratio (o/e) 0.73, 90% interval 0.66 to 0.82. Synonymous variants: 115 observed, 120.64 expected, observed/expected ratio (o/e) 0.95, 90% interval 0.82 to 1.11.
Homologues: Orthologues: chimpanzee IL1B (99% identical), macaque IL1B (90% identical), mouse Il1b (68% identical), rat Il1b (67% identical), guinea pig IL1B (65% identical), dog IL1B (64% identical), rabbit IL1B (62% identical), pig IL1B2 (58% identical), tropical clawed frog il1b (35% identical), zebrafish il1b (19% identical), zebrafish il1fma (15% identical). Paralogues in human: IL36B (17% identical), IL1RN (17% identical), IL36A (16% identical), IL36G (16% identical), IL36RN (15% identical), IL37 (14% identical), IL1F10 (12% identical).
Diseases named in the same sentence as IL1B in open-access papers:
IL1B is named in the same sentence as 1,638 diseases in open-access papers, as found by Europe PMC text mining. Sharing a sentence is not in itself a finding about the gene and the disease. The quoted sentences say what the papers report.
colitis (1,638 papers, 1995 to 2026). Inflammation of the colon. "XXLP significantly improved colitis symptoms, including weight loss and colon shortening, and reduced the concentrations of inflammatory markers IL-1β, IL-18, TNF-α, and IL-6." (PMID 41901297, 2026). "Generally, the development of TNBS-induced colitis was associated with an increase in the local production of IL-12, TNFα, and IL-1β." (PMID 40305159, 2025). "Prophylactic N5 administration alleviated colitis symptoms (weight loss, colon shortening), reduced fecal and serum lipocalin-2 levels, and suppressed colonic pro-inflammatory cytokines (IL-1β, IL-6)." (PMID 40813467, 2025). "Inflammatory cytokines, such as TNF-α, IL-1β, and IL-6, are central mediators of the mucosal immune response and are closely linked to the pathogenesis of colitis-stimulated inflammation." (PMID 41614862, 2025). "The correlation of albuminuria, Lcn2, and Il‐1β expression with colitis markers strengthens the implication of causality between a gut‐barrier defect and kidney inflammation in this model." (PMID 40018982, 2025). "AhR activation has been linked to the alleviation of colitis by reducing inflammatory cytokines like IL‐1β, IL‐6, and TNF‐α, while enhancing anti‐inflammatory cytokines, such as IL‐4, IL‐10, and IL‐22, and strengthening the intestinal epithelial barrier." (PMID 39836604, 2025). "Gut bacteria, such as Prevotella, Akkermansia muciniphila, and Proteus mirabilis, increase macrophages and IL-1β production, exacerbating colitis susceptibility." (PMID 40678521, 2025). "Mice treated with fucoidan exhibited significant protection from colitis, evidenced by longer colonic length, less weight loss, and lower expression levels of inflammatory genes such as Il‐1b, Il‐18, Il‐6, Nos2, and Tnfα." (PMID 40545965, 2025). "An upsurge in the pro-inflammatory cytokines such as IL-6 and IL-1β in the colitis condition has been linked with chronic colitis." (PMID 37695333, 2024). "To this end, we analyzed the main pro-inflammatory cytokines associated with DSS-induced colitis, such TNFα, IL-1β, IL-12p40, and IL-6, at the transcription level." (PMID 39456254, 2024). "Accordingly, we found that the expression of the genes encoding for IL-1b and IL-17, two major cytokines that play a pathogenic role in colitis, was also reduced in the colonic mucosa of Cth–/– mice." (PMID 39427081, 2024). "Ectopic colonization of these oral pathobionts promotes IL-1β production via activation of inflammasome in macrophages, leading to the development of colitis in genetically susceptible mice." (PMID 38443988, 2024). "Among them, the NLRP3 pathway has been shown to activate GSDMD in a mouse model of colitis-associated colon cancer and mediate the release of IL-1β and IL-18." (PMID 38898209, 2024). "Another study has found that Cardamonin treatment attenuated intestinal disorders, including recurrent colitis and colitis-associated tumors, and reduced IL-1β and TNF-α secretion." (PMID 38473179, 2024). "Blocking IL-1β in a murine model of colitis and associated colon cancer significantly reduces the size and invasiveness of tumors, which indicates a significant role of this cytokine in the development and progression of colorectal cancer." (PMID 37569878, 2023). "sakei K040706 isolated from soybean paste has been reported to inhibit pro-inflammatory factors such as nitric oxide (NO), TNF-α, IL-1β, and IL-6 and reduce inflammatory cell infiltration, thereby weakening the severity of colitis caused by DSS in mice." (PMID 36766113, 2023). "Similar to the results in the CFA-induced arthritis model, colitis ameliorated the histopathological severity of knee joint arthritis caused by mBSA and recombinant IL-1β." (PMID 36793721, 2023). "The colitis was exacerbated in these animals, as evidenced by a reduced colon length associated with increased colonic mRNA expression and protein levels of IL-1β, IL-4, IL-12, IL-13, IFNγ and TNF-α." (PMID 37996842, 2023).
colitis (continued). "Macrophage-specific Ptpn2 deletion is known to protect against colitis-associated tumor formation in mice in an inflammasome and IL1β-dependent manner." (PMID 36968224, 2023). "Our study revealed an increase in Il1β expression by Socs3-deficient neutrophils at the RNA level during DSS-induced colitis." (PMID 37283760, 2023). "Concretely, PTSO was tested in two experimental models of colitis, which were associated with the regulation of cytokines in inflamed colonic tissue, leading to a reduction of pro-inflammatory cytokines IL-1β, TNF-α, and IL-6." (PMID 36986093, 2023). "A study in 2017 found that the anomalously activated NLRP3 inflammasome caused the local increased production of IL-1β, induced regulatory T cells and maintained gut homeostasis through remodeling the gut microbiota to resist the colitis." (PMID 37833958, 2023). "Expression of TNF receptor 1 Tnfr1, the proinflammatory cytokine Il1β and the adaptor protein Myd88 were also increased during experimental colitis in MCJ-deficient mice." (PMID 37805634, 2023). "Perinatal exposure to TiO2 also exacerbated the colitis, as evidenced by a reduced colon length associated with increased colonic mRNA expression and protein levels of IL-1β, IL-4, IL-12, IL-13, IFNγ and TNF-α." (PMID 37996842, 2023). "Enriched A. muciniphila eroded the mucus layer, impairing the intestinal barrier, which in turn posed greater susceptibility to colitis in mice, and induced excessive secretion of inflammatory cytokines (IL-1β, IL-6, and TNF-α)." (PMID 36312913, 2022). "Colitis induction in untreated rats caused necrotic effects in colon tissues, a significant increase in colonic IL-1β, TNF-α, MPO, and MDA levels, and a remarkable decrease in GSH and TAC levels in colon tissue in comparison to the control group." (PMID 35428860, 2022). "Wang and his colleagues found that depletion of neutrophil or blockade of IL-1β activity significantly reduced mucosal damage and tumor formation in a colitis-associated cancer (CAC) mice model." (PMID 35215376, 2022). "Here we provide novel information that this colitis-associated increase in IL-1β expression is driven by α4β7-mediated leukocyte adhesive interactions with cerebral endothelium." (PMID 35379260, 2022). "ATG16L1 deficiency in hematopoietic or myeloid cells renders mice more susceptible to experimental colitis due to hyperactivation of pan inflammatory responses including the inflammasome and IL1β/IL18 processing." (PMID 37425656, 2022). "Studies using mouse models have found TET2 loss to be associated with elevated cytokines/chemokines, resulting in increased susceptibility to colitis and IL-1β dependent atherosclerosis." (PMID 35228982, 2022). "Impaired intestinal barrier integrity is another essential feature of colitis and is caused by aberrant IL-1β and TNF-α levels." (PMID 35126813, 2022). "Enterobacteriaceae induce interleukin (IL)-8 and IL-1β secretion and cause colitis with increasing intestinal inflammation." (PMID 35183234, 2022). "In a colitis animal model induced by dextran sulfate sodium (DSS) and 2,4,6-trinitrobenzene sulfonic acid, maresin-1 suppressed disease activity in colitis and improved weight loss by decreasing IL-1β, TNF-α, IL-6, and IFN-γ in the acute phase." (PMID 35163291, 2022). "IL-1β is also identified as a significant factor in oral-pathogen mediated gut inflammation, as treatment with IL-1 receptor antagonist largely attenuated colitis in germ-free mice colonized with a periodontitis-associated oral microbiota." (PMID 34950607, 2021). "For hemidesmosomes, total and conditional KO mice for integrin α6β4 were generated and led to spontaneous colitis caused by detachment from the basal membrane and the underlying lamina propria that induces an IL-1β/IL-18 pro-inflammatory response." (PMID 34943865, 2021). "The mechanism of EA to attenuate colitis is associated with the inactivation of the NLRP3/IL-1β pathway and improvement of the Nrf2/HO-1 pathway." (PMID 35095910, 2021).
colitis (continued). "Development of colitis was associated with a 3- to 60-fold increase in mRNA expression levels of pro-inflammatory cytokines including IL-1β, tumor necrosis factor (TNF)-α, interferon (IFN)-γ, IL-17, and IL-22." (PMID 34299013, 2021). "Cytokines associated with colitis inflammation (IL-1β, IL-6, and IL-17A) are significantly inhibited after treatment with M2b macrophage exosomes." (PMID 34683937, 2021). "These Th17 cells of oral origin can be activated by translocated oral pathobionts and cause the development of colitis when in the gut through IL-1β." (PMID 34501547, 2021). "FMTs from patients with IBD/D+ or IBD/D− caused IBD-like colitis in the transplanted mice: they increased the myeloperoxidase activity, IL-1β and IL-6 expression, and NF-κB+/CD11c+ cell population in the colon." (PMID 34650107, 2021). "Abnormal intestinal immune response is one of the characteristics of UC, and TNF-α and IL-1β are pro-inflammatory mediators caused by the immune response of colitis." (PMID 34208038, 2021). "The FMTs from patients with IBD/D+ or IBD/D− all caused colitis in mice: they significantly induced colon shortening; upregulated myeloperoxidase activity, IL-1β and IL-6 expression and increased the NF-κB+/CD11c+ cell population in the colon." (PMID 34650107, 2021). "In contrast, an autoimmunity-associated PTPN22 variant (V619W) that leads to increased PTPN22 function causes increased NLRP3 inflammasome activation and excess IL-1β production that protects mice from experimental colitis." (PMID 33808793, 2021). "Colitis-susceptible germ-free mice colonized with dysbiotic oral microbiotas from mice subjected to ligature-induced periodontitis displayed increased IL-1β signatures compared with germ-free mice colonized with healthy oral microbiotas." (PMID 34950607, 2021). "After treatment with HMC, colitis improvement was associated with the rise in colon antioxidant status and the inhibition of pro-inflammatory cytokines IL-1β, IL-6, IL-33, and TNF-α in the colon." (PMID 33499333, 2021). "Our present study revealed that ASK1 deficiency in myeloid lineage caused macrophage apoptosis and IL-1β secretion, which is consistent with our previous study of colitis model." (PMID 33542169, 2020). "These bacteria additionally caused colitis, including colon shortening, myeloperoxidase activity, and IL-1β expression in the colon." (PMID 32669127, 2020). "In TPH1 deficient colitis mice, the severity of colitis and the level of IL-1β, IL-6, and tumor necrosis factor (TNF)-α was clearly reduced, and reloading 5-HT increased the severity of DSS-induced colitis." (PMID 32117308, 2020). "In the present study, the development of colitis and C. glabrata overgrowth were associated with high expression of IL-1β and down-regulation of IL-10." (PMID 32661259, 2020). "IL-1β is a potent inflammatory cytokine that is implicated in the development of colitis and inflammatory responses in the gut." (PMID 31935236, 2020). "Paenalcaligenes hominis treatment also caused colitis, including colon shortening and an increase in the myeloperoxidase activity, IL-1β expression, and NF-κB+/CD11c+ cell population in the colon." (PMID 32669127, 2020). "MiR-223−/− mice exhibit exacerbated DSS-induced colitis and an increased level of IL-1β through the loss of repressive function on NLRP3 targeted by miR-223-3p." (PMID 30755244, 2019). "Mice deficient in NLRP3, Casp1/11, ASC, and IL-1β have all demonstrated an increased susceptibility to DSS-induced colitis, disease exacerbation and more frequent mortality when compared to WT mice." (PMID 30873162, 2019). "Dizocilpine, particularly with intermediate dose of 1mg/kg significantly improved animal’s weight loss as well as macroscopic and microscopic signs of colitis, reduced colonic levels of IL-1β, IL-6, TNF-α and MPO activity." (PMID 32641944, 2019).